IL6 (interleukin 6)
Diseases named in the same sentence as IL6 in open-access papers (continued):
Sharing a sentence is not in itself a finding about the gene and the disease.
psoriasis (continued). "IL-6 cytokine, one of the cytokine secreted by keratinocytes, has been reported to be involved in many inflammatory skin conditions including autoinflammatory and allergic disorders such as psoriasis, atopic dermatitis and urticaria." (PMID 30012134, 2018). "Activated macrophages in adipose tissue stimulate adipocytes to secrete inflammatory mediators such as TNF-α, IL-1, IL-6, and IL-8 which may account for some of the pathologic changes observed in psoriasis patients." (PMID 29680995, 2018). "The role of IL-6 in keratinocyte differentiation and in the pathogenesis of psoriasis was so far unknown; here we showed that IL-6 expression is augmented in the epidermis of lesioned skin from psoriasis patients." (PMID 30219085, 2018). "In psoriasis, Compound 5c reduced IL-6, IL-8, IL-1β and IL-24 in imiquimod-stimulated models." (PMID 30301277, 2018). "In psoriasis, high expression levels of IL-6 lead to increased acivation of p-ERK1/2." (PMID 30219085, 2018). "Taken together, our study demonstrates that let-7b regulates keratinocyte differentiation through targeting IL-6-dependent ERK1/2 signaling that may play an important role in the pathogenesis of psoriasis." (PMID 30219085, 2018). "A diet and exercise intervention was also found to reduce concentrations of TNF-α, IL-6, IL-8, C-reactive protein and monocyte chemoattractant protein 1, which may contribute to improvement of psoriasis." (PMID 29680995, 2018). "However, IL-6 expression was significantly decreased in all epidermal layers in psoriasis lesions of let-7bTG mice." (PMID 30219085, 2018). "Our result reveals a previously unknown mechanism for regulation of IL-6 levels during psoriasis by let-7b and highlights a critical role for the ERK1/2 signaling pathway in epidermal differentiation during psoriasis." (PMID 30219085, 2018). "IL-6 plays a fundamental role in driving the differentiation of naive T lymphocytes into Th17 cells, and indeed, Th17 T lymphocytes are generally believed to play a central role in the pathogenesis of psoriasis." (PMID 29316631, 2018). "Activated macrophages in adipose tissue stimulate adipocytes to secrete TNF-α, IL-1, IL-6, and IL-8, which may contribute to the development of psoriasis." (PMID 29680995, 2018). "Our findings reveal a previously unknown mechanism for an homoeostatic let-7b-IL-6 axis whilst highlighting a critical role of ERK1/2 signaling in epidermal differentiation of psoriasis." (PMID 30219085, 2018). "The present meta-analysis found that TNF-α, IFN-γ, sE-selectin, IL-2, IL-6, IL-8, IL-18, IL-22, fibrinogen and C3 were elevated in serum of patients with psoriasis, indicating that serum levels of these cytokines may correlate to their levels in tissue." (PMID 29416693, 2018). "Moreover, IL-6, IL-21, IL-22, IL-26, and IL-29, which participate to the amplification and maintenance of the inflammatory loop in psoriasis, all signal via STAT3." (PMID 29316631, 2018). "Anti-psoriasis mechanism studies have indicated that compound 5c reduced the secretion of IL-1β, IL-6, IL-8 and IL-24 in an IMQ-stimulated model and could also attenuate the activation of IMQ-induced MAPKs, including JNK1/2 and ERK1/2." (PMID 30301277, 2018). "In the serum of patients with psoriasis, the level of IL-6 is highly elevated." (PMID 29358932, 2017). "Thus, anti-IL-6 mAb has been proposed to be a novel therapeutic option for the treatment of psoriasis." (PMID 29358932, 2017). "Unexpectedly, in GILZ-Tg mice, the severity of IMQ-induced psoriasis-like skin lesions as well as induction of cytokines commonly up-regulated in human psoriasis (Il-17, Il-22, Il-23, Il-6, S100a8/a9, and Stat3) was significantly more pronounced relative to GILZ-Wt mice." (PMID 27934944, 2016). "During psoriasis, IL-6 is primarily released by keratinocytes." (PMID 26999594, 2016). "As IL-6 has a central role in the development of psoriasis, this cytokine could serve as a potential target in the treatment of this disease." (PMID 26999594, 2016).
psoriasis (continued). "In addition to Th17 cells producing IL-6 in lesions from psoriasis patients, DCs and endothelial cells produce IL-6 as well, dampening Treg suppression." (PMID 27242798, 2016). "Recently, we demonstrated that IL-6 is upregulated in IMQ-induced psoriasis-like skin disease." (PMID 26999594, 2016). "A recent study revealed that NRIP1 may stimulate the activity of NF-κB by forming a trimeric complex with RelA and CBP, and upregulate downstream inflammatory genes, including TNF-α and IL-6, both of which play crucial roles in the pathogenesis of psoriasis." (PMID 27708240, 2016). "Thus, IL-6 signaling must be compensated by other signaling cascades in IMQ-induced psoriasis—as the trans-signaling of IL-6." (PMID 26999594, 2016). "Furthermore, serum levels of IL-6 are elevated in patients with psoriasis and IL-6 leads to a stronger proliferation of human keratinocytes." (PMID 26999594, 2016). "Recent data suggests that IL-6 plays an important role in the pathogenesis of psoriasis." (PMID 26999594, 2016). "IL6 is well known to be involved in the pathogenesis of psoriasis." (PMID 25897967, 2015). "Curcumin could also demonstrate the inhibitory effect in lmiquimod-induced psoriasis-like inflammation by decreasing the levels of IL-1β and IL-6." (PMID 26007179, 2015). "Besides, STAT3 transgenic mice and SOCS3 knockout mice (the negative regulator of STAT3) have constitutive activation of STAT3 and both develop murine IL-6-driven psoriasis." (PMID 26136626, 2015). "Both erucin and sulforaphane were shown to be involved in the prevention and in the therapy of psoriasis and inflammatory skin diseases through the down-regulation of psoriasis-related cytokines, interleukin (IL)-12/23p40, IL-6 and tumor necrosis factor (TNF)-α." (PMID 24736897, 2014). "It seems that inflammatory mediators may be involved in insulin resistance, such as TNF-α, Il-6, leptin, adiponectin, mediators that are also disturbed in psoriasis (further detailed below)." (PMID 25713604, 2014). "Increased skin and serum IL-6 levels are a feature of psoriasis." (PMID 25126586, 2014). "Activated macrophages in the adipose tissue stimulate adipocytes to secrete adipocytokines (adipokines), such as TNF-α, IL-6, leptin, and visfatin, which may also play a role in the pathogenesis of psoriasis." (PMID 25713604, 2014). "Additionally, IL-6-mediated pSTAT3 signaling is capable of enhancing keratinocyte growth and proliferation, promoting psoriasis epidermal hyperplasia; IL-6 signaling on keratinocytes also induces chemoattractant proteins via AP-1 downstream activation." (PMID 25126586, 2014). "In addition, psoriasis is characterized by local and systemic increases in levels of proinflammatory cytokines, such as interleukin-6 (IL-6) and tumor necrosis factor-alpha (TNF-α)." (PMID 25587268, 2014). "Specifically, glutamine consumption enhances the production of many cytokines, and among them, tumor necrosis factor-α (TNF-α), interferon-γ (IFN-γ), interleukin-1β (IL-1β), and interleukin-6 (IL-6), all of which play an important role in psoriasis innate immunity." (PMID 25580230, 2014). "Increased serum levels of IL-6 have been reported in psoriasis patients." (PMID 24803721, 2014). "However, IL-6 overexpression is also related with the pathogenesis of several types of skin diseases, including psoriasis and systemic lupus." (PMID 24757670, 2014). "IL-23-induced dermal inflammation in psoriasis mouse models relies on T cells and IL-6." (PMID 25126586, 2014). "Increased IL-6 levels in psoriasis patients could be due to a significant disruption of the skin barrier and the associated enhanced risk of pathogen invasion that promotes the synthesis of IL-6 by immune cells." (PMID 23531535, 2013). "The levels of IL-6 in serum and in skin blister fluids correlate with the severity of psoriasis." (PMID 23531535, 2013).
psoriasis (continued). "Also, mice with psoriasis had significant increases in specific pro-inflammatory cytokines (IL-1β, IL-6 and IL-12) and decreases in the anti-inflammatory cytokine (IL-10) after PSD, which were normalized after 48 h of sleep rebound." (PMID 23226485, 2012). "Our findings thus suggest that psoriasis mouse models can be differentiated with respect to a TNF-α/IFN-γ/IL-6 axis, which ultimately, may be reflective of disparities in the abundance of certain TNF-generating immunocytes (e.g., macrophages, DCs or T-cells)." (PMID 21483750, 2011). "Similarly, the pathogenesis of psoriasis involves key Th1 and Th17 inducing cytokines like TNFα, IL-1β, IL-2, IL-6, IL-10, IL-12p70, IL-23, CCL2, 3, 4, 5, 20, CXCL1, 8, 9 and 10, many of which are induced by cocktail treated DCs." (PMID 20663192, 2010). "Circulating serum IL-6 has been shown to be elevated in multiple inflammatory diseases including RA, systemic juvenile idiopathic arthritis, systemic lupus erythematosus, ankylosing spondylitis, psoriasis and Crohn's disease." (PMID 19368720, 2009). "Literature data point out increased serum IL-6 and IL-8 levelsin psoriasis." (PMID 16864908, 2006). "In psoriasis, various stress-related triggers—ranging from environmental factors to genetic predispositions—can activate innate immune cells and keratinocytes to produce tumor necrosis factor-α (TNF-α), interferon-γ (IFN-γ), IFN-α, interleukin-6 (IL-6), and interleukin-1β (IL-1β)." (PMID 40731810, 2025). "Additionally, IL-6 and IL-22 levels may serve as reliable biomarkers for monitoring treatment efficacy in psoriasis patients." (PMID 40699767, 2025). "Psoriasis is mediated by T lymphocytes, in particular Th1 and Th17, and dendritic cells that are activated and elevated in skin lesions and migrate and release proinflammatory cytokines such as IL-1 and IL-6, but also TNF-a, which favor keratinocyte proliferation and inflammation." (PMID 40003621, 2025). "Thus, the proinflammatory effect of IL-6 and the resistance to Treg suppression may plays a key role in the pathogenesis of psoriasis." (PMID 38405187, 2024). "Also, obstructive sleep apnoea and inflammatory skin disorders, such as psoriasis, pemphigus, urticaria and atopic dermatitis, share a common inflammatory substrate with high levels of interleukin-6 and tumour necrosis factor, likely paving the way for the onset of sleep disturbances." (PMID 38397620, 2024). "In addition, elevated levels of IL-6 can also be observed in patients with T1D, RA and psoriasis." (PMID 39544933, 2024). "Of note, IL-6-induced effects, which are deleterious in patients affected by psoriasis, could be instead protective in the cancer context and limit tumor growth and expansion, by promoting expansion of cytotoxic IL-17-producing T cells and preventing immune suppression by Treg." (PMID 38495872, 2024). "However, inhibition of IL-6 may lead to compensatory proinflammatory effects of other cytokines making anti-IL-6 therapy ineffective for psoriasis." (PMID 39328313, 2024). "When environmental and genetic factors activate plasmacytoid dendritic cells, cytokines such as TNF-α, IL-6, and IL-1β are released, leading to T cell-mediated inflammation, keratinocyte activation, and excessive proliferation, resulting in inflamed skin patches characteristic of psoriasis." (PMID 39170985, 2024). "Thus, the IL‐6/AKT/STAT3/LMO4 pathway is a potential therapeutic target for psoriasis treatment." (PMID 38156380, 2023). "IL-6, a traditional cytokine in psoriasis, may exert a controversial effect on psoriasis." (PMID 38008779, 2023). "Our findings indicate that suppressing SIRT3 exacerbated IMQ-induced psoriasis-like inflammation by upregulating the levels of acetylated XBP1s, which subsequently enhanced its total protein levels and transcriptional activity and increased the production of IL-23a, IL-6, and TNF-α cytokines." (PMID 37275851, 2023).
psoriasis (continued). "This IFN-κ production during normal wound healing may regulate keratinocyte inflammatory cytokines (i.e., IFN-β, IFN-α, IL-6) secretion through a positive feedforward loop, which has been demonstrated in other chronic skin diseases, such as lupus and psoriasis." (PMID 35358091, 2022). "Thus, the results obtained in our study with quebecol and its derivatives indicate that the acanthosis and hyperplasia features of psoriasis could be mediated via the inhibition of IL-6 and TNF-α production." (PMID 35745702, 2022). "Sleep deprivation in mouse models of psoriasis led to increased levels of pro‐inflammatory cytokines, including IL‐1β, IL‐6 and IL‐12, resulting in enhanced inflammatory immune response and suggesting that circadian disruption could contribute to the pathogenesis of psoriasis." (PMID 35851722, 2022). "pDC-derived IL-6 may offer a plausible mechanism to explain pDC’s puzzling role in psoriasis." (PMID 34215755, 2021). "Th17 cells, as well as Th1 cells and keratinocytes, secrete TNF-α, IFN-γ, IL-1β, IL-6, IL-12, IL-17A, IL-22, IL-23 participating in pathophysiologic processes of psoriasis and current biological therapies as T cell-directed agents have demonstrated excellent efficacy in psoriasis." (PMID 33685393, 2021). "Moreover, an obviously improvement in M1-related inflammation medicators (TNF-α, IL-6, NO and iNOs) and suppression in M2-related anti-inflammation cytokines (IL-10 and Arg-1) emerged in psoriasis lesions in the skins of IMQ-treated mouse, which was consistent with previous reports." (PMID 33858431, 2021). "A very recent study in a mouse model of psoriasis-like inflammation suggests that IL-6 may be part of a loop that links metabolic alteration into the keratinocyte compartment with inflammatory cytokine production and the initiation events of the psoriatic plaque formation." (PMID 34006909, 2021). "IL-6 may be anti-inflammatory during early phase of psoriasis, when pDCs were heavily recruited." (PMID 34215755, 2021). "However, genetic deletion of IL-6 can worsen psoriasis in certain animal models." (PMID 34215755, 2021). "Thus, we hypothesize that IL-6 may play differential roles during early and late stages of psoriasis pathogenesis." (PMID 34215755, 2021). "Furthermore, both TNF-α and IL-6 can induce IL-24 production in psoriasis." (PMID 34638757, 2021). "Importantly, there were not any differences between MR16-1-treatment and IgG Ctrl-treatment in littermate Ctrl mice, highlighting the significance of IL-6 blockade therapy for the regulation of PD-1 signal blockade-activated CD8 T cells in psoriasis-like dermatitis." (PMID 33060784, 2020). "By using a murine model of imiquimod-induced psoriasis-like dermatitis, we further demonstrated that PD-1 deficiency accelerates skin inflammation with activated cytotoxic CD8 T cells into the epidermis, which engage in pathogenic cross-talk with keratinocytes resulting in production of IL-6." (PMID 33060784, 2020). "The pathogenesis of psoriasis seems to be driven by the interaction between innate immune cells, adaptive immune cells and keratinocytes, in a process mediated by cytokines (including interleukins (IL)-6, IL-17 and IL-22, interferon and tumor necrosis factor) and other signaling molecules." (PMID 32224981, 2020). "In the DEX group, the expressions of IL-1β, IL-6, TNF-α, IL-17, and IL-22 were significantly lower than the model group (p < 0.05), suggesting that the expressions of inflammatory cytokines associated with psoriasis have been inhibited after the intervention of DEX." (PMID 32090080, 2020). "MiR-26 may be involved in the development of IL-6 mediated psoriasis." (PMID 32811699, 2020). "According to a cross-sectional study, psoriasis patients had increased proinflammatory macrophage type 1 (IL-1, IL-6, TNF-α), Th1 (IL-2, IL-12, IFN-γ), Th17 (IL-6, IL-17) but also anti-inflammatory Th2/T regulatory (Treg) (IL-4, IL-10) profiles which may be correlated to the severity of psoriasis." (PMID 31649677, 2019).
psoriasis (continued). "Although the direct action of MHP1-AcN on IL-23 and its effects in the IL-23-induced psoriasis model need further studies, one of the preventative effects of MHP1-AcN on psoriasis may be associated with the inhibition of TLR7/8-induced IL-6 and IL-23 expression." (PMID 31659208, 2019). "In conclusion, serum levels of TNF-α, IFN-γ, IL-2, IL-6, IL-8, IL-18, IL-22, chemerin, lipocalin-2, resistin, sE-selectin, fibrinogen and C3 were significantly elevated and serum level of adiponectin was significantly decreased in psoriasis patients compared to healthy individuals." (PMID 29416693, 2018). "Targeting IL-6 signaling in psoriasis may enhance immunosuppression by Tregs." (PMID 30258447, 2018). "Moreover, IL-6 was found to be up-regulated in human psoriasis skin lesions compared with healthy skin, suggesting that IL-6 might have a relationship with psoriasis presumably via let-7b expression levels." (PMID 30219085, 2018). "Furthermore, Il-6 signaling on keratinocytes seems to be important in the context of psoriasis." (PMID 26999594, 2016). "In fact, in a mouse model of imiquimod-induced psoriasis-like inflammation, topical curcumin was demonstrated to improve the skin lesions with an effect comparable to that of clobetasol and to significantly decrease the cutaneous levels of IL-17A, IL-17F, IL-22, IL-1β, IL-6, and TNF-α mRNA." (PMID 26090395, 2015). "In addition, keratinocytes in psoriasis as well as synoviocytes in RA are capable of responding to direct IL-36 ligands stimulation with production of IL-6, IL-8, and antimicrobial peptides, which cooperate with IL-17A and TNF-alpha promoting neutrophil activation and migration." (PMID 25126586, 2014). "However, the magnitude of the IL-6 response was attenuated in many RA patients before brodalumab administration, with a lower magnitude of IL-6 mRNA production compared to healthy volunteers or psoriasis patients." (PMID 24286136, 2013). "In addition, blockade of IL-23 signaling using a monoclonal antibody (ustekinumab) against the p40 subunit of IL-12 and IL-23 has been shown to be effective in Crohn's disease, psoriasis and psoriatic arthritis with results similar to those seen when blocking IL-6 or TNFα." (PMID 22229105, 2012). "Bearing in mind that this interleukin actssynergistically with IL-1 and tumor necrosis factor alpha(TNF-α) further supports the hypothesis that IL-6 maycontribute via its receptor action to epidermal growth factor(EGF) function in modulating cell hyperproliferation in psoriasis." (PMID 16864908, 2006). "This prospective study investigated the effects of brodalumab on serum cytokine levels—specifically IL-6, IL-17A, IFN-α, IFN-γ, and TNF-α—and their correlation with disease severity as assessed by Psoriasis Area and Severity Index (PASI)." (PMID 41516330, 2026). "For chronic pruritus, LCN2 modulates the excitability of pruritus-related neurons via pathways such as the IL-6/STAT3 axis, and participates in the pathological processes of pruritus in allergic contact dermatitis, xerosis, atopic dermatitis, and psoriasis." (PMID 42088581, 2026). "Fibroblast-derived cytokines, like IL-6 and TGF-β, regulate T cell differentiation (notably, Th17 in psoriasis), while regulatory T cells (Tregs) can suppress fibroblast inflammatory function." (PMID 41598494, 2026). "Biologics targeting IL-6, IL-17, and TNF-α have demonstrated efficacy in psoriasis, and their effects likely extend to fibroblast populations." (PMID 41598494, 2026). "In this study, we investigated serum levels of IL-6, IL-17A, IFN-α, IFN-γ, and TNF-α in patients with psoriasis before and after treatment with brodalumab, all of whom had previously failed therapy with TNF-α inhibitors." (PMID 41516330, 2026). "Since IL-10 inhibits production of pro-inflammatory cytokines such as IL-1, IL-6, and TNF-α, it can be useful for reducing inflammatory skin conditions, like psoriasis." (PMID 41465292, 2025).